LINC00665 (long independently transcribed non-coding RNA 665)
Diseases named in the same sentence as LINC00665 in open-access papers (continued):
Sharing a sentence is not in itself a finding about the gene and the disease.
cancer (continued). "In conclusion, LINC00665 may be an important driver of cancer cell resistance to gefitinib, cisplatin, and gemcitabine, and has the potential to predict the efficacy of cisplatin-paclitaxel neoadjuvant chemotherapy." (PMID 35563845, 2022). "The LINC00665 described in this review is abnormally expressed in various human cancers and may become a new marker for cancer diagnosis." (PMID 35356290, 2022). "In conclusion, LINC00665 is an lncRNA that affects several aspects of carcinogenesis, particularly in response to both chemotherapeutic agents and small molecules that are used in targeted cancer therapy." (PMID 36429005, 2022). "Functional experiments showed that high expression of LINC00665 could regulate cancer progression by affecting biological processes, such as cancer cell proliferation, apoptosis, migration, and invasion." (PMID 35563845, 2022). "LINC00665 was upregulated in eighteen cancers and downregulated in two cancers." (PMID 35563845, 2022). "In addition, abnormal expression of LINC00665 is also significantly correlated with the prognosis of cancer patients and the treatment outcomes of several chemotherapeutic drugs." (PMID 35563845, 2022). "All these findings indicate that LINC00665 has a key function in cancer." (PMID 35664776, 2022). "In the future, it is necessary to broaden the role of LINC00665 in cancer." (PMID 35563845, 2022). "This was consistent with the biological roles of LINC00665 in other cancers." (PMID 33407473, 2021). "Recently, LINC00665 role in cancers has been revealed gradually." (PMID 34232917, 2021). "Even though these findings highlighted the potential value of LINC00665 in cancer therapy, it remains unknown whether and how LINC00665 could regulate the progression of AML." (PMID 33658535, 2021). "Database analysis also revealed that LINC00665 is overexpressed in hepatocellular carcinoma and might contribute to cancer progression by regulating cell cycle pathways." (PMID 31907362, 2020). "Recently, a growing number of studies have found that LINC00665, a long intergenic non-protein coding RNA, may be associated with various cancers, including gastrointestinal tumors, gynecological tumors, and respiratory neoplasms." (PMID 35664776, 2022). "LINC00665 may be a potential prognostic biomarker and novel therapeutic target for cancers." (PMID 35664776, 2022). "Moreover, correlation analysis results elucidated that LINC00665 negatively correlates with miR-195-5p in LUAD, which partially reversed LINC00665 overexpression-mediated malignant phenotypes, such as proliferation, invasion, and migration of cancer cells in LUAD." (PMID 34277412, 2021). "Mechanistically, LINC00665 was found to recruit the transcription factor TCF7, known for its involvement in cancer-related signaling pathways, to promote the transcription of HHLA2." (PMID 38951802, 2024). "The host gene LINC00665 is known to regulate EMT in cancer, and alcohol stimulates the EMT program in cancer cells, which leads to cancer progression." (PMID 37217680, 2023). "The discovery of the NF-κB/LINC00665/PKR/NF-κB loop provided a way to understand the connection between inflammation and cancer." (PMID 35356290, 2022). "Long intergenic non-protein coding RNA 665 (LINC00665) has been proven as an oncogene in several cancers, but its function in CRC is still unclear." (PMID 35101035, 2022). "LINC00665 is a newly identified lncRNA which has been studied in several cancers but not in OS." (PMID 34306997, 2021).
LINC00665 also shares sentences with these, for which no sentence is quoted: digestive system tumors (2 papers); lung squamous cell carcinoma (2); alcoholic liver diseases (1); Cerebral ischemia (1); cervical cancer (1); colon adenocarcinoma (1); glioblastoma (1); gynecological tumors (1); retinoblastoma (1); thymic epithelial tumor (1).